Y_RNA (Y RNA )
Gene: Miscellaneous RNA gene on chromosome 12 (49,132,853 to 49,132,947, reverse strand). Ensembl gene ENSG00000200309.
Homologues: Orthologues: chimpanzee Y_RNA (92% identical), guinea pig Y_RNA (84% identical). Paralogues in human: RNY4 (89% identical), RNY4P10 (88% identical), RNY4P7 (88% identical), RNY4P13 (86% identical), RNY4P6 (86% identical), RNY4P25 (85% identical), RNY4P36 (85% identical), RNY4P9 (85% identical), Y_RNA (85% identical), RNY4P19 (84% identical), RNY4P27 (84% identical), RNY4P37 (84% identical), and 88 more.